FANCA (FA complementation group A)
Diseases named in the same sentence as FANCA in open-access papers (continued):
Sharing a sentence is not in itself a finding about the gene and the disease.
tumor (continued). "This patient had six verified tumor mutations (ARID1B, ATM, CDK8, FANCA, and two RASA1 mutations), all of which were detected in the preoperative plasma sample." (PMID 30554450, 2019). "FANCA localises to 16q24.3 and is a plausible tumour suppressor gene candidate because of its role in the repair of DNA damage." (PMID 15860134, 2005). "Furthermore,in vivo experiments demonstrated that FANCA plays a promotional role in the tumor progression of GC." (PMID 38682160, 2024). "In Case 7, SMARCB1 and FANCA variants were detected in the majority of cells (62–92%) in both regions; however, the VAF of an ATR variant (0.28 and 0.13 in Regions A and B, respectively) indicated that this was a later event in the development of this tumour." (PMID 39766052, 2024). "FANCA, in turn, facilitates the advancement of GC cells by modulating malignancies such as proliferation, migration, and invasion, indicating its potential as a promoter of tumor progression in GC." (PMID 38682160, 2024). "As proven in the present study, the list of genes from the 44-gene panel more frequently mutated in BOT compared to the other tumor groups (FANCB, SEM1, FANCA, BRCA2, CHEK2, MUTYH, RAD50) was much longer than analogically altered genes in the hot-spot panel (KRAS only)." (PMID 39456660, 2024). "This may indicate that the interaction of FAAP20 with FANCA functions as a tumor suppressor specifically in TNBC, which could involve the SSA function of FAAP20/FANCA that we have observed." (PMID 37620397, 2023). "RNA-seq of tumour xenografts identified FANCA as a direct miR-361-3p target, and validation suggested miR-361-3p inhibitor effects might be mediated in part through FANCA modulation." (PMID 36622663, 2023). "Three pathogenic variants were identified: c.1320+1G>A in the CDH1 gene and c.27_28insCCCAGCCCCAGCTACCA (p.Ala9fs) of the VEGFA gene were found only in the tumor tissue, whereas c.G1874C (p.Cys625Ser) in the FANCA gene was found in both the tumor and normal tissue." (PMID 36833207, 2023). "It seemed that ACVR2A, FANCA, RBM10, and SPTA1 mutations might have important functions in tumour development for different subtypes and different molecular characteristics in Chinese patients." (PMID 38024139, 2023). "The third patient (case No. 4) carrying a BRCA1 and an FANCA mutation in the tumor had progressive disease after initiation of PARPi." (PMID 37173992, 2023). "By a-CGH analysis on tumor DNA at progression, we found the loss 12p13.31, containing KLRB1 gene, the loss 16p11.2 containing MAPK3 gene, and the loss 16q11.2–q24.3, containing FANCA gene." (PMID 35742955, 2022). "Our results suggest that this probably also applies to NB, even if it was not the case of our patient, who did not benefit from the tumor loss of FANCA gene, possibly because his clinical picture was too compromised." (PMID 35742955, 2022). "Next-generation sequencing identified homodeletion of FANCA in the tumor tissue." (PMID 31931827, 2020). "The specific HRR mutations identified in the 21 tumour samples were: BRIP1 (n = 5), CDK12 (n = 3), RAD54L (n = 2), RAD51B (n = 2), RAD54L rearr (n = 1), ATM rearr (n = 1), FANCA rearr (n = 1), FANCD2 (n = 1), FANCL rearr (n = 1), FANCL (n = 1), RAD51C (n = 1), RAD52 del (n = 1), XRCC3 rearr (n = 1)." (PMID 30353044, 2018). "FANCA, higher expression correlated with an improved outcome that could be a consequence of a less malignant phenotype, due to a more stable tumor genome." (PMID 23825533, 2013). "Consequently, our investigation aimed to ascertain whether FANCA could stimulate the cell cycle pathway to facilitate tumor development." (PMID 38682160, 2024). "This can be explained by the frequent identification of several alterations that point towards identical treatment recommendations (e.g., BRCA mutation, ATM underexpression, FANCI, FANCA deletion for PARP inhibitors in the same patient) but were not always all named by both tumor boards." (PMID 36274133, 2022).
tumor (continued). "We further knocked down FANCA and FANCD2 in DLD1-P cells to investigate if their depletions sensitize tumor cells to E7820." (PMID 38789724, 2024). "However, the established role of FANCA, SLX4, BRCA2, and ATRX in DNA repair pathways is unlikely to be coincidental, especially considering that we identified mutations in other DNA repair pathway genes, including ATR, which was mutated in two tumours in our study." (PMID 39766052, 2024). "These included 11q22.2 silent FA-HNSCC, VU1131-T, the 11q22.2 gained/amplified FA-HNSCCs, VU1604-T, VU974-T and VU1365-T, as well as the non-tumor 11q22.2 silent ARPE-19-hTERT WT and FANCA.KO." (PMID 34997070, 2022). "We propose that FANCA-mutant clones from CAL27 and CAL33 are good tools to deepen into molecular mechanisms of tumor progression mediated by FA genes." (PMID 33918752, 2021). "To evaluate the degree of FANCA-BRCA1 co-expression, we measured the correlation coefficient of FANCA and BRCA1 expression in the Rb-tumor cohort." (PMID 25161863, 2014). "Possible candidates CBFA2T3, TERF2 and TERF2IP, FBXL8 and LRRC29 and FANCA were studied for insertion and deletion mutations and for expression differences using quantitative RT-PCR in a panel of tumour cell lines and primary tumours with and without loss of 16q." (PMID 16280054, 2005). "Remarkably, pathogenic variants in BRCA1/2 were present in patients both with and without clinical benefit, whereas variants in other known homologous recombination repair (HRR) genes were identified exclusively in tumor samples from patients with clinical benefit (ABRAXAS1, FANCA, and RAD51C)." (PMID 39591206, 2024). "In numerous phase II and III clinical studies, little or no response to multiple PARPi was reported in diverse tumor types carrying HR mutations in genes such as CHEK2, ATM, FANCA, and CDK12." (PMID 37761329, 2023). "Interestingly, when adding the E2F3 expression to the FANCA and BRCA1 gene expression correlation, tumor samples with relatively low expression of FANCA and BRCA1 had also low E2F3 and vice versa." (PMID 25161863, 2014).
FANCA also shares sentences with these, for which no sentence is quoted: Fanconi anemia complementation group A (8 papers); genetic disease (5); myeloid neoplasm (3); aplastic anemia (2); autosomal recessive disease (2); endometrial cancer (2); haematologic disorder (2); medulloblastoma (2); metastatic disease (2); Pancytopenia (2); retinoblastoma (2); skin cancer (2); acute kidney injury (1); acute promyelocytic leukemia (1); alcoholic liver diseases (1); Alpha-thalassemia (1); Alzheimer disease (1); Azoospermia (1); Beaulieu–Boycott–Innes syndrome (1); benign tumors (1); bladder cancer (1); Bloom syndrome (1); bone marrow failure syndrome (1); bowel cancer (1); childhood cancer (1); cholangiocarcinoma (1); Cohen syndrome (1); colon adenocarcinoma (1); colon cancer (1); colorectal cancer (1).
A further 53 diseases each share a sentence with FANCA in 1 paper.